IL1B (interleukin 1 beta)
Diseases named in the same sentence as IL1B in open-access papers (continued):
Sharing a sentence is not in itself a finding about the gene and the disease.
tumor (continued). "Interestingly strong trends towards increased plasma levels of cytokines and chemokines associated with protective anti-tumor immunity was also evident including: IL-1b, IL-12, MIP1a, MIP1b, MCP-1, IL-15, IFNγ, IFNα, IL-1R, IP-10, MIG, IL-8." (PMID 31426803, 2019). "IL-1β can be produced directly by tumors or by tumor associated leukocytes." (PMID 31174326, 2019). "Signaling pathways downstream of IL-1R1 activation might have an important role in cancer-induced behavioral changes, given that cortical and hippocampal IL-1β increases are associated with behavioral outcomes in several other tumor rodent models." (PMID 31019214, 2019). "Indeed, clear associations have been demonstrated between IL-1β and angiogenesis in multiple tumor types." (PMID 31231372, 2019). "Additionally, deficiency or inhibition of IL-1β signaling in TME has been shown to inhibit tumor angiogenesis and metastasis in mouse models of lung metastases-induced by various metastatic cells regardless of species of origin." (PMID 30832375, 2019). "Tumor-promoting inflammation is emerging as a therapeutic target and one of the hallmarks of cancer, and prolonged stimulation with inflammatory cytokines, including IL-1β, has been implicated in the generation and accumulation of MDSCs." (PMID 30683126, 2019). "Taken together, glucose supply could be associated with IL-1β production in tumor-bearing mice and could affect tumor development and metastasis." (PMID 30586442, 2018). "Notably, the triggering of tumor-associated pDCs with the NLRP3 activator caused elevated IL-1β levels." (PMID 30447690, 2018). "Candidate factors include tumor-secreted molecules previously implicated in MDCS formation, such as GM-CSF, VEGF, IL-1β, IL-6, and prostaglandin E2, but other tumor-derived factors may be involved." (PMID 30235890, 2018). "In case of APC-restricted inflammasome activation these agents may be well suited to exploit the beneficial effects of APC-associated IL-1β for tumor therapy." (PMID 29983861, 2018). "Interestingly, the enhanced tumor incidence encountered in Asc−/− mice was associated with a significant attenuation of Il-1β and Il-18 levels in the colon within the tumor tissue." (PMID 29868004, 2018). "In our CID model, tumour burden was associated with increased IL-6, and possibly IL-1β." (PMID 28120908, 2017). "Furthermore, the cytokines IL-6 and IL-1β, previously associated with tumor growth and metastasis, were also up-regulated in both the cell lysate and the supernatant of LuM cells, confirming the results of the expression array analysis." (PMID 28410227, 2017). "Interestingly, dual incubation with LPS and a caspase-1 inhibitor ablated the increase in tumour cell adhesion to endothelial cell monolayers and was associated with a large reduction (62–83%) in the amount of IL-1β present in the macrophage-conditioned media." (PMID 28551814, 2017). "As with endothelial cell stimulation, 24-h IL-1β stimulation of tumour cells alone caused significant increase of both MDA-MB-231 and MCF7 adhesion to blood and lymphatic endothelial cells with MDA-MB-231 tumour cells having a significantly higher level of adhesion to lymphatic endothelial cells." (PMID 28551814, 2017). "IL-1β is a multifunctional pro-inflammatory cytokine principally produced by hematopoietic cells such as macrophages and monocytes, and also by epithelial cells, and expression is associated with angiogenesis and the invasive abilities of tumour cells." (PMID 28551814, 2017). "Both LCN2 and IL-1β are linked to lymphangiogenesis and tumor metastasis." (PMID 28804221, 2017). "The expression of inflammatory-associated cytokines, including IL-1α, IL-1β and IL-6, were significantly reduced in the tumor microenvironment of JC-001-treated mice, suggesting that JC-001 might decrease tumor-induced inflammation." (PMID 28399860, 2017).
tumor (continued). "Likewise, IL-1R antagonist deficient mice, secreting the excessive level of IL-1β, exist rapid tumor development and high tumor frequency." (PMID 28938606, 2017). "We therefore evaluated whether the anti-tumor activity of LFs was associated with its anti-inflammatory properties through inhibiting pro-inflammatory cytokines and mediators (IL-1β, IL-6, TNF-α, iNOS and Cox-2)." (PMID 27563884, 2016). "In this study, only ASC, but not the other inflammasome-associated molecules NRLP3, CASP1 and IL-1β was strongly associated with the clinicopathological characteristics (e.g. tumor stage and node stage) and was an independent predictor of OS, DSS, and DFS of OSCC patients." (PMID 27367024, 2016). "In three studies, increased levels of IL-1β were associated with poor prognosis: metastasis, shorter survival, and when analysed together with IL-6, was associated with poor overall survival and tumor progression." (PMID 27170998, 2016). "Pro-inflammatory macrophages are generally characterized by the production of high levels of pro-inflammatory mediators, such as TNF-α, IL1-β, IL-6 or IL-12 and are associated with bacterial clearance and tumour cytotoxicity, being considered tumour suppressors." (PMID 27513864, 2016). "IL-1β may associate with these genes to generate a programmed, tumor favorable microenvironment during oral carcinogenesis." (PMID 26831400, 2016). "IL-1β is expressed by tumor-associated macrophages (TAMs) and neutrophils." (PMID 27148488, 2016). "Progression in tumor stage and size are associated with high levels of IL-1β, IL-6 and TNF-α." (PMID 27507058, 2016). "To test whether inflammasome-mediated IL-1β production is linked to tumor progression, we measured IL-1β levels in tumor tissues." (PMID 27786298, 2016). "Microtubule destabilizers, such as these, potentially alter HLA expression by upregulating the production of cytokines (IFNα, IL-1β, IL-6, IL-12) involved in HLA expression or disrupt intracellular trafficking of HLA proteins, causing redistribution at the tumor surface." (PMID 27854240, 2016). "As for BrafV600E cells, COX-deficiency was associated with a shift in the inflammatory profile at the tumor site, with reduced expression of tumor promoting factors, such as Il6 or Il1b and increased levels of mediators associated with anti-tumor immune pathways." (PMID 26343581, 2015). "Compared with their lower metastatic counterparts, the highly metastatic tumors formed by this cell line expressed higher amounts of interleukin (IL)-1α, with similarly augmented expression of IL-1α and IL-1β by tumor stromal cells and of VEGF-A and VEGF-C by tumor-associated macrophages." (PMID 24924428, 2014). "This inhibition of tumour growth was paralleled by a >40% decrease in polymorphonuclear cell numbers, and the up-regulation of associated pro-inflammatory cytokines including IL-1α, IL-1β as well as COX2, all of which promote gastric tumourigenesis." (PMID 24804649, 2014). "IL-1β is a potent pro-inflammatory cytokine associated with tumor growth and angiogenesis." (PMID 24273542, 2013). "Mutated BRAF also promotes the secretion of IL-1α and IL-1β, innate inflammatory mediators which can drive tumor cells to protect themselves from immune attack by up-regulating molecules that inhibit the function of anti-tumor lymphocytes." (PMID 24829749, 2013). "Recent studies indicate that IL1B is associated with tumor invasiveness and metastasis." (PMID 20096140, 2010). "Additionally, analysis of preoperative biomarkers revealed a significant negative correlation between interleukin-1β (IL-1β) and TRG (ρ = –0.75, p = 0.013; τ = –0.60, p = 0.027), indicating that higher preoperative IL-1β levels tended to be associated with better tumor regression." (PMID 41601630, 2026).
tumor (continued). "On the other hand, Jun can stimulate apoptosis in a range of cancer cell types and play a tumour-suppressing role, for example, in a manner inversely related to JunD or by transcriptional regulation of senescence- and inflammation-associated genes including IL-1β, TNFα, CCL3 and CCL8." (PMID 39859271, 2025). "Furthermore, analysis of cytokine expression and the migration and proliferation profiles of PC3 cells indicated that PC3-EVs impact differentiated THP-1 macrophages, showing that PC3 cells contain an active NLRP3 inflammasome cascade and secrete IL-1β, which is associated with tumor staging." (PMID 40718836, 2025). "Similarly, IL-1B, mostly secreted from tumor-associated macrophages as a pro-inflammatory cytokine, enhances the expression of ELF3 in LUADs with EGFR mutations, leading to the activation of the PI3K/Akt/NF-κB pathway and consequently contributes to tumor progression." (PMID 38983267, 2024). "Reduced IL-1β, IL-6, and IL-8 concentrations in the salivary supernatant fluid of patients with cancerReduction in Bacteroidetes species in cancer subjectsUp-regulation of genes associated with differentiation and T-cell recruitment to the tumor microenvironment." (PMID 37892459, 2023). "In addition, in an in vitro model of carcinogenesis, it was observed that calcitriol may promote the sensitivity of tumour cells to TRAIL-induced apoptosis by inhibiting the production of interleukin (IL)-1β by tumour associated macrophages (TAMs)." (PMID 37299554, 2023). "Likewise, myeloid cell-derived IL-1β is associated with anti-tumor immunity in patients." (PMID 36932407, 2023). "Inflammasomes are protein signaling complexes of immune-stromal cells and tumor cells that are in response to damage- and pathogen-associated molecular patterns (DAMPs and PAMPs) and trigger the release of inflammatory cytokines such as interleukin-1β (IL-1β) to participate in immune defense." (PMID 38031068, 2023). "Moreover, loss of tumour cell‐derived IL‐1β signalling in tumour stroma significantly enhances CD8+ cytotoxic T cell infiltration and activation followed by attenuating pancreatic tumour growth, suggesting CD8+ T cells are the key component with antitumor immunity." (PMID 36124714, 2022). "During pyroptosis, activation of inflammasomes can promote the maturation and release of inflammatory factors such as IL-18, IL-1β, IL-10, etc. which may inhibit antitumor immune effects or cause an inflammatory cascade response, thereby promoting tumor development under particular circumstances." (PMID 35725836, 2022). "More so, the acceleration of dysplasia by the HFD in the IL1β mice was associated with a shift in the gut microbiota supporting our hypothesis that tumor formation in this model in our hands was accelerated due to the eradication of microbiome during rederivation." (PMID 36233047, 2022). "Notably, the reduced burdens of cancer cells in glucan-administered mice resulted in lower serum IL-1β and IL-6 (the cytokines that might be associated with tumor growth)." (PMID 36142859, 2022). "Interestingly, the high expression of a SASP gene expression profile, in particular the SASP component IL1B, was associated with a high progression-free survival rate, independently of the status of tumor resection, showing that the SASP can also have anti-tumorigenic effects." (PMID 36291792, 2022). "Although presence of IL-1β has been closely linked to tumor progression and metastasis in various types of cancer, the role of NLRP3 inflammasome activation remains controversial, suggesting that other functional roles of inflammasome, beyond secretion of pro-inflammatory mediators, may exist." (PMID 36032139, 2022). "Here, we suggest that increased primary tumour growth upon IL-1B inhibition in the microenvironment is associated with microenvironment-derived IL-1B promoting the infiltration of innate immune cells that may display anti-tumour functions." (PMID 34290237, 2021).
tumor (continued). "Pathogenic microorganisms and tumor cells can be eliminated by M1 macrophages by acute proinflammatory response, immune activation reaction, and cytophagy through the release of proinflammatory factors, such as NO, IL-1β, IL-6, TNF-α, and chemokines such as CCL2, CCL3, CCL5, CXCL9, and CXCL10." (PMID 34506209, 2021). "Finally, we observed that stromal factors such as IL-6 and IL1B may underlie the different effects of the involvement of MMP2-positive BMDCs in tumor invasion." (PMID 35008304, 2021). "Therefore, we sought to assess whether tumor-associated NLRP3 activity also affects the IL-1β/IL-6/STAT3 axis in host myeloid cells." (PMID 34531850, 2021). "Interestingly, several other cytokines reported to be associated with senescence maintenance and tumor-suppression, such as IL1α, IL1β, TGF-β, and CCL5, exhibited upregulated expression in the LY2835219 monotherapy group but did not exhibit downregulated expression in the combination group." (PMID 33116117, 2020). "Moreover, the association of anti-IL-1β and anti-PD-1 mAbs inhibits tumor growth." (PMID 33261061, 2020). "Thus, IL-1β has been associated with all steps of malignancy (carcinogenesis, progression, invasion, and metastasis) and may even be expressed by the tumor cells." (PMID 31167479, 2019). "The origin of the tumor immunosuppression could be in part mediated by the hypoxia and acidosis within the TME, the metabolic restriction imposed by the high energy demand of the tumor or an epigenetic reprogramming of immune cells, all these mechanisms being intimately linked to IL-1β secretion." (PMID 30832375, 2019). "Furthermore, IL-1β levels were linked to the glucose supply in tumor-bearing mice." (PMID 30586442, 2018). "In particular, IL-1β facilitated a self-sustaining loop of crosstalk between adipocytes, tumor-associated neutrophils and fibrogenic pancreatic stellate cells that enhanced desmoplasia, limited vascular perfusion, impaired chemotherapeutics and accelerated tumor growth." (PMID 30567335, 2018). "In light of the behavioural effect of 5-ASA/SP treatment on the SPT despite failure to prevent tumour-associated increases in IL-1β and IL-6, an investigation of a wider array of inflammatory markers might help clarify the observed behavioural effects of these drugs in our model." (PMID 28120908, 2017). "IL-1β is one of the most potent pro-inflammatory cytokines influencing the growth and invasion of nearly all types of tumor cells due to its abundance in tumor site and patients serum in contrast to IL-α, which is mainly membrane-associated and less diffusible in tumor microenvironment." (PMID 28927416, 2017). "However, tumor tissues from caspase-1 deficient mice had reduced levels of IL-1β." (PMID 27786298, 2016). "Thus, we hypothesized that myeloid cells contribute to tumor-associated inflammation and tumor progression through the production of IL-1β and other inflammatory mediators." (PMID 27786298, 2016). "Notably, cDC2s, either isolated from the tumour site or from tdLNs, were unique in their Th17-inducing capacity, which is likely to be linked with their high production of the Th17-inducing cytokines IL-23, IL-1β and IL-6." (PMID 28008905, 2016). "If the level of secreted IL-1β can be suppressed (suppression of angiogenesis) and the expression of membrane associated IL-1α increased (development of anti-tumor immunity) in parallel in tumors, the anti-tumor effect of IL-1 might be augmented." (PMID 28548063, 2014). "In order to determine whether stabilization of Snail by macrophages/IL-1β contributes to their ability to drive Wnt signaling, we silenced Snail in tumor cells, and examined the ability of macrophages and IL-1β to induce Wnt signaling in Snail deficient HCT116 and Hke-3 cells." (PMID 20661477, 2010).
tumor (continued). "In the context of neoplasia, the production of growth factors such as GM‐CSF and G‐CSF, along with inflammatory cytokines like IL‐1β, IL‐6 and IL‐17, is increased by tumour cells, tumour‐infiltrating leukocytes and tumour‐associated stromal cells." (PMID 41503514, 2026). "In its subnetwork, leptin is linked to HIF‐1α, IL‐1β, and IL‐6, suggesting some influence over the control of those drivers' downstream effects such as EMT and tumor invasion." (PMID 41450167, 2026). "Treg cells with GPX4 knocked out enhance the TH17 cell response by secreting IL‐1β, promoting the body's anti‐tumor immune function." (PMID 41560416, 2026). "The localized heat triggers pyroptosis, releasing DAMPs (IL‐18, IL‐1β, and tumor antigens), which enhance tumor immunogenicity." (PMID 41298282, 2026). "Compared with the MCC + NIR group, because of the positive regulatory effect of antimicrobial peptides on the inflammatory tumour microenvironment, there were also significant differences in the expression levels of IL-6 and IL-1β in the PfCC+NIR group." (PMID 41484054, 2026). "The failure of IL-1β blockade as an adjuvant or metastatic treatment emphasized a likely unique “hit-and-run” role of IL-1β during the earliest stages of tumor initiation." (PMID 42001483, 2026). "Though FNG is primarily produced by the liver in response to cytokines like IL‐6 and IL‐1β, our data suggest that tumor‐derived cytokines also contribute to elevated FNG." (PMID 41549214, 2026). "We show that, in the context of chemo-immunotherapy, IL-1β enhances anti-tumor immunity by inducing tumor-cell CXCL10 expression and recruiting CD8+ T cells, thereby sensitizing "cold" tumors to treatment." (PMID 41694383, 2026). "The TME itself modulates Th17 plasticity, with chemokines such as CCL20, CCL17, and CCL22 recruiting Th17 cells, while tumor-derived cytokines such as IL-1β, IL-6, IL-23, and TGF-β promote their differentiation." (PMID 41486167, 2026). "Comparisons between OSCC tissues and normal oral mucosa consistently reveal elevated expression of NLRP3, caspase-1, and IL-1β, which correlate with advanced tumor stage, lymph node metastasis, and poor clinical prognosis." (PMID 41596738, 2026). "M1 cells are characterized by a pro-inflammatory phenotype; they express CD80, CD86, CD40, and inducible nitric oxide synthase (iNOS), produce pro-inflammatory cytokines (IL-1β, TNFα), and provide anti-infective and anti-tumor activity." (PMID 41596489, 2026). "IL-1β upregulates vascular endothelial growth factor expression and induces endothelial activation, thereby promoting neovascularization and supporting tumor expansion." (PMID 41596738, 2026). "IL‐1β is capable of inducing NETosis, whereas the formation of NETs can cause TGF‐β‐dependent EMT and chemotherapy resistance in tumour cells." (PMID 41503514, 2026). "Even though IL-1β is considered a marker of M-1-like macrophages that activates a tumor-targeted immune response, anomalous inflammasome activation in TAMs causes metastasis in different tumors." (PMID 40141358, 2025). "This activation leads to the release of IL-1β and IL-18, which, in turn, influences the expression of PD-L1 on tumor cells and contributes to the recruitment of immune-suppressive cells within the TME." (PMID 40141358, 2025). "Neutrophils were the main source of IL‐1β in the lungs of 4T1 tumor‐bearing mice exposed to chronic stress." (PMID 39630109, 2025). "On the other hand, IL-1β contributes to tumor angiogenesis and invasiveness in the process of PCa progression." (PMID 40427694, 2025). "PANoptosis triggers the release of a large number of inflammatory factors (such as IL-1β and IL-18), which significantly enhance anti-tumor immunity and can help reverse the immunosuppressive microenvironment typically induced by necroptosis alone." (PMID 40721869, 2025). "IL-1β is secreted primarily by activated monocytes, macrophages, and neutrophils, though tumor and stromal cells can also produce it." (PMID 40940992, 2025).